SPINDOC (spindlin interactor and repressor of chromatin binding)
Description:
Chromatin protein that stabilizes SPIN1 and enhances its association with histone H3 trimethylated at both 'Lys-4' and 'Lys-9' (H3K4me3K9me3). Positively regulates poly-ADP-ribosylation in response to DNA damage; acts by facilitating PARP1 ADP-ribosyltransferase activity.
Synonyms: SPIN-DOC; C11orf84
Tractability: Small molecule: a structure with a bound ligand is known. PROTAC: UniProt records ubiquitination sites on it; ubiquitination databases record sites on it.
Gene: Protein-coding gene on chromosome 11 (63,813,433 to 63,827,718, forward strand). Ensembl gene ENSG00000168005.
Subcellular location: Nucleus; Chromosome
Subcellular location (Human Protein Atlas): Nuclear speckles
Gene Ontology:
Molecular function: protein binding
Biological process: DNA damage response; negative regulation of DNA-templated transcription; regulation of protein ADP-ribosylation
Cellular component: chromosome; nucleus; site of DNA damage
Genetic constraint (gnomAD): Loss-of-function variants: 16 observed, 29.5 expected, observed/expected ratio (o/e) 0.54, 90% interval 0.37 to 0.82. The upper end of that interval is the gene's LOEUF score, 0.82, which puts it in group 3 of 6, group 1 being the genes least tolerant of losing a copy. Missense variants: 413 observed, 500.47 expected, observed/expected ratio (o/e) 0.83, 90% interval 0.76 to 0.89. Synonymous variants: 215 observed, 202.71 expected, observed/expected ratio (o/e) 1.06, 90% interval 0.95 to 1.19.
Homologues: Orthologues: chimpanzee SPINDOC (99% identical), macaque SPINDOC (98% identical), pig SPINDOC (88% identical), dog SPINDOC (88% identical), guinea pig SPINDOC (85% identical), rat Spindoc (82% identical), mouse Spindoc (82% identical), rabbit SPINDOC (74% identical).
Diseases named in the same sentence as SPINDOC in open-access papers:
SPINDOC is named in the same sentence as 2 diseases in open-access papers, as found by Europe PMC text mining. Sharing a sentence is not in itself a finding about the gene and the disease.
SPINDOC shares sentences with these, for which no sentence is quoted: cancer (1 paper); tumor (1).